DNAJC5G (DnaJ heat shock protein family (Hsp40) member C5 gamma)
Synonyms: CSP-gamma; FLJ40417
Tractability: No criterion of Open Targets' tractability assessment is met for any kind of drug.
Gene: Protein-coding gene on chromosome 2 (27,275,433 to 27,281,499, forward strand). Ensembl gene ENSG00000163793.
Subcellular location: Membrane
Gene Ontology:
Cellular component: cytoplasm; membrane
Genetic constraint (gnomAD): Loss-of-function variants: 13 observed, 20.28 expected, observed/expected ratio (o/e) 0.64, 90% interval 0.42 to 1.02. The upper end of that interval is the gene's LOEUF score, 1.02, which puts it in group 4 of 6, group 1 being the genes least tolerant of losing a copy. Missense variants: 245 observed, 242.77 expected, observed/expected ratio (o/e) 1.01, 90% interval 0.91 to 1.12. Synonymous variants: 81 observed, 89.05 expected, observed/expected ratio (o/e) 0.91, 90% interval 0.76 to 1.09.
Homologues: Orthologues: chimpanzee DNAJC5G (96% identical), macaque DNAJC5G (92% identical), dog DNAJC5G (75% identical), guinea pig DNAJC5G (67% identical), rabbit DNAJC5G (67% identical), pig DNAJC5G (67% identical), rat Dnajc5g (60% identical), mouse Dnajc5g (58% identical), tropical clawed frog dnajc5g (45% identical), zebrafish dnajc5ga (44% identical), zebrafish dnajc5gb (44% identical), Drosophila melanogaster Csp (41% identical), and 15 more. Paralogues in human: DNAJC5 (45% identical), DNAJC5B (41% identical), DNAJC21 (30% identical), DNAJC13 (25% identical), DNAJC10 (25% identical), DNAJC11 (25% identical), DNAJC16 (24% identical), DNAJC18 (23% identical), DNAJC14 (21% identical), DNAJC7 (20% identical), DNAJC17 (19% identical), DNAJC25 (19% identical), and 8 more.
Diseases named in the same sentence as DNAJC5G in open-access papers:
DNAJC5G is named in the same sentence as 1 disease in open-access papers, as found by Europe PMC text mining. Sharing a sentence is not in itself a finding about the gene and the disease.
DNAJC5G shares sentences with these, for which no sentence is quoted: tumour (1 paper).